TNF (tumor necrosis factor)
Diseases named in the same sentence as TNF in open-access papers (continued):
Sharing a sentence is not in itself a finding about the gene and the disease.
tumor (continued). "Additionally, tumor cells induce the secretion of inflammatory factors, including VEGF, tumor necrosis factor-α (TNF-α), TGF-β and interleukins, to stimulate myeloid cells and immune cells to migrate, thus amplifying inflammatory factor secretion." (PMID 33396739, 2020). "This was suggested to be mediated through TNF-α, as tumour burden was not increased in Bcl-3/TNF-α double KO mice." (PMID 31930327, 2020). "The primary anti-tumor activities of CTL involves their killing of target cells via the exocytosis of cytotoxic granules containing perforin and granzymes as well as the production of cytokines such as IFNγ and tumor necrosis factor (TNF)." (PMID 33013886, 2020). "In TAMs-tumor cells in vitro co-culture model, tumor necrosis factor-related apoptosis-inducing ligand (TRAIL) reprograms TAMs to M1-like phenotype by inducing expression of proinflammatory cytokines like IL1B, IL6, TNFα." (PMID 32219066, 2020). "Entolimod injected 1 h before D-GalN alone did not affect BNL tumor growth, indicating that the tumor suppression observed with TNF/D-GalN in entolimod-treated mice was due to TNF activity." (PMID 32027657, 2020). "TNFα production by HLADR+ intermediate monocyte was also affected in CCA patients before tumor resection, but not in HCC patients." (PMID 32256215, 2020). "In addition, the expression of several cytokines, including interferon-γ (IFN-γ), tumor necrosis factor-α (TNF-α), interleukin-4 (IL-4), and IL-10, had been determined in the IDO shRNA-treated LLC1-tumor bearing mice in our previous study." (PMID 32933162, 2020). "TNF-α, one of the main cytokines in the TME, has a context-dependent role in tumor growth." (PMID 32973519, 2020). "Furthermore, we detected higher levels of IFN-γ and TNF-α expression in tumor-infiltrating CD4+ and CD8+ T cells in Fip200–/– tumor-bearing mice compared with WT tumor-bearing mice." (PMID 32780724, 2020). "In this study, a higher percentage of SHP-1–/– CD8 T cells secreted IFNγ and TNFα, which might be one of the mechanisms by which SHP-1–/– CD8 T cells were able to eliminate tumor cells more efficiently." (PMID 33425916, 2020). "Interestingly, a low concentration (10 μM) of metformin stimulated exhausted tumor-infiltrating CD8+ T cells to upregulate IL-2, TNF-α, and IFN-γ and potentiated anti-tumor activity." (PMID 33613560, 2020). "Indeed other cytokines such as IL-2, IL-2, TNF-α, and IFN-γ are thought to regulate the metastatic tumor niche and play a key role in regulating cells of the immune system recruited into this environment." (PMID 31771091, 2019). "Karbach reported that the bacterial vaccine increased levels of immunoregulatory cytokines including interleukin (IL)-6, tumor necrosis factor (TNF)-α, IFN-γ, and IL1-β, which may be involved in inducing tumor regression." (PMID 30693030, 2019). "There is controversy; however, regarding the role of TNF-α in cancer, the pro- or antitumoral TNF-α response with in the tumor microenvironment depends not only on local concentration but also on its expression site in the tumor." (PMID 31788012, 2019). "The results showed that both anti-inflammatory cytokines, such as IL-4 and IL-10, were up-regulated in tumours derived from animals that had previous exposure with the EDC, while the expression of the pro-inflammatory counterpart (TNF-α and IFN-γ) was diminished." (PMID 31731436, 2019). "So too, EVs carrying death-inducing cytotoxic cytokines TNF, TNF-related apoptosis-inducing ligand, TRAIL, and Fas ligand (FasL) induces apoptosis of tumor-specific T cells, and exosomal EVs block NKG2D to inhibit NK cell activation and NK tumoricidal activity." (PMID 30895170, 2019). "In the residual tumor, the overexpression region of CCL2 and TNFα overlapped closely." (PMID 31780645, 2019). "Furthermore, previous reports have demonstrated that the pro-inflammatory cytokine, TNF-α, is able to stimulate EMT in a various range of tumor cells." (PMID 30917533, 2019).
tumor (continued). "Tumor-secreted factors such as GM-CSF, IL-1β, IL-6, TGF-β, and TNF mediate expansion of MDSCs." (PMID 32039025, 2019). "Three fractions of RT also significantly increased the plasma concentrations of IL-6 and TNFα in the normal mice, but not in the tumor-bearing mice." (PMID 31752313, 2019). "The in vivo mechanism(s) by which these MHC class I-restricted CD4+ T cells mediate anti-tumor effects could be further investigated by in vivo blockade of IFN-γ, TNF-α or IL-2, or by using IFN-γR or TNF-αR knockdown cancer cells." (PMID 30626427, 2019). "Further studies will be necessary to investigate strategies of converting the TNF-α/TNFR2 signaling to the induction of Th9 cells but not Treg cells in tumor immunotherapy." (PMID 30717817, 2019). "Despite its various pharmacological activities, the molecular mechanism of dicentrine on TNF-α-induced tumor progression has not been adequately elucidated." (PMID 31766230, 2019). "Furthermore, the anti-tumor CD8+ T cells can kill MDSCs via production of TNF-α, IFN-γ, or the expression of apoptotic FasL, and thereby reduce MDSC tumor infiltration." (PMID 30873170, 2019). "After antigen recognition, activation, and proliferation, CD4+ cells synthesize and secrete interleukin-2 (IL-2), human interferon-C (IFN-C), and tumor necrosis factor (TNF), which can dissolve and directly kill tumor cells by recognizing and binding antigens on tumors through antigen receptors." (PMID 31781277, 2019). "After TNF-α/NF-κB1 being successfully abrogated by BAY 11–7082, anti-angiogenic treatment-induced CD47 upregulation was diminished in NSCLC tumors and produced increased anti-tumor effect." (PMID 31829270, 2019). "It was suggested that CD4+ cells kill tumor cells through a mechanism that did not involve Fas/FasL or TNF-α, but was dependent on the TNF-α related apoptosis inducing ligand (TRAIL)." (PMID 31379821, 2019). "NK cells can attack tumor cells by releasing pro-apoptotic factors, including TNF-α and Tumor necrosis factor-related apoptosis-inducing ligand (TRAIL), or cytokines capable of inhibiting tumor cell proliferation and promoting the inflammatory response, such as IFN-γ." (PMID 30930851, 2019). "Single intraperitoneal administration of NDEA significantly (p < 0.05) elevated liver function enzymes ALT, AST, GGT, LDH, ALP, TBA, TBil, and levels of tumor markers CEA, AFP, TSGF, TNF‐α in serum compared to normal control rats, suggesting the presence of metabolic disorders in NDEA group animals." (PMID 31428352, 2019). "Thus, TIGIT and DNAM-1 can compete for binding to PVR and Nectin-2 which are highly expressed on tumour cells and are also upregulated by exposure to cytokines, such as IFN-γ and TNF-α." (PMID 30626155, 2019). "Additional effects of paclitaxel include the triggering of macrophages for TNFα and IL-1 production and its antiangiogenic activity by downregulating VEGF and Ang-1 expression in tumor cells and by increasing the secretion of TSP-1 in the tumor microenvironment." (PMID 35582143, 2019). "TNF-α expression was lower in the brain of KD-R-fed mice than in the brain of SD-UR-fed mice, whereas TNF-α expression was even lower in the KD-R + DON-treated mice, suggesting a minimum amount of tumour load and reduced inflammation compared to the other two groups." (PMID 31149644, 2019). "However, serum concentrations of TNF‐α and IFN‐γ were elevated in mice receiving CAH (+) in comparison with untreated tumor‐bearing mice." (PMID 30886812, 2019). "TANs mainly suppress anti-tumor immunity via interacting with CD8+ T cells, inducing CD8+ T cells apoptosis through nitric oxide (NO) production mediated by tumor necrosis factor-α (TNF-α)." (PMID 31500650, 2019). "The involvement of TNF-α/NF-κB and IL6/Stat3 pathways in tumorigenesis have been confirmed in a series of mouse models of GI malignancy focusing on inflammatory network of the tumor microenvironment." (PMID 31100828, 2019).
tumor (continued). "TNFα‐CSG treatment did not affect protease gene expression in tumour CD11b+ cells or in cultured 4T1 tumour cells (with the exception of MMP3) (Fig EV4A)." (PMID 31709774, 2019). "These SLX-Lipo-ICG could accumulate in the regions of inflammation or tumor owing to the interaction of SLX and E-selectin, which enhanced E-selectin expression by inflammatory cytokines, such as TNF, in vascular endothelial cells." (PMID 31426531, 2019). "sPD-1(soluble PD-1), interacting with PD-L1, could prevent PD-1 from binding with PD-L1 and promote effective tumor immunity, possibly resulting from decreased IL-10, TGF-β and increased IL-2 TNF-α and IFN-γ." (PMID 31708918, 2019). "This likely reflected a cascade of proTα-induced effects that relates to: (i) TNF-α production by peritoneal macrophages, (ii) enhancement of antitumor NK cell cytotoxicity, and (iii) generation of MHC-restricted tumor-specific CD8+ cytotoxic T-cell responses in an IL-2-dependent manner." (PMID 31717548, 2019). "Changes in Ca2+ signalling may also impair cytokine production, including Interferon (IFN)-γ and Tumor Necrosis Factor (TNF), therefore interfering with systemic inflammation and anti-tumour responses." (PMID 31014226, 2019). "Moreover, under the influence of CD4+ Th1 and Th2 cells in tumor microenvironment, TIBs polarize into Be-1 cells that produce IFN-γ, IL-12, and TNF-α or Be-2 cells that produce IL-2, IL-4, TNF-α, and IL-6." (PMID 31662750, 2019). "Tumor samples from HPK1 KD mice demonstrated significantly upregulated key immune cell markers involved in mediating anti-tumor immunity, including CD4, CD8, IFNγ, TNFα, Granzyme B, CD28, CD11c and CD11b." (PMID 30913212, 2019). "Although the immune responses were not statistically different through CD8+IFN-γ+ or CD8+TNFα+ T cells, complete protection from tumor challenge was observed only in mice vaccinated with the M2 vaccine vector." (PMID 30764846, 2019). "Moreover, lung infiltrated T cells in piTRL-treated mice that were cured from the 1st transplanted tumor produced much higher amounts of IFN-γ and TNF-α in response to cancer Ag." (PMID 31412934, 2019). "Furthermore, ibrutinib diminishes intracellular interactions of CLL cells with surrounding microenvironment cells despite synthesis of tumor promoting cytokines such as B cell activating factor (BAFF), tumor necrosis factor alpha (TNFα) or CD40 ligand." (PMID 31766355, 2019). "We performed multiplex immuno-assay (Luminex) to assess the presence of inflammatory cytokines involved in the regulation NK cells function, such as TNF-α, IFN-γ, IL-6, IL-15, and IL-1β, in the tumor microenvironment (black bars) and in the healthy adjacent tissue microenvironment (white bars)." (PMID 31105699, 2019). "In this study, the sensitivity of tumor xenografts to paclitaxel was increased as TNF-α levels increased, suggesting that TNF-α may function in tumor immune surveillance." (PMID 31117164, 2019). "The main mechanisms that eliminate tumor cells in CRC are gamma IFN and TNF (α and β) producing CD4 + TH1 cells and IL10 secreted by FoxP3+ regulatory T cells by NK or γδ T cells that suppress or downregulate induction and proliferation of effector T cells at the tumor site." (PMID 31303863, 2019). "Cell-specific analyses complemented these results by indicating that NOTCH1, NOTCH2 and NOTCH3 were up-regulated by TNFα in the tumor cells but not in the MSCs." (PMID 31105691, 2019). "As expected, TNF is not restricted to the tumor microenvironment and can signal to the brain via humoral routes." (PMID 31174326, 2019). "This is in line with previous data that various TNF and TNFR family members are upregulated on NK cells in the context of malignant disease, where they modulate antitumor reactivity upon interaction with their cognate counterparts on tumor cells." (PMID 30813611, 2019).
tumor (continued). "Furthermore, we found that MK2KD in tumor milieu mimicking hypoxic conditions stabilized p27 and mitogen-activated protein kinase phosphatase-1 (MKP-1) but destabilized TNF-α." (PMID 31023373, 2019). "Besides IFN-γ, we also examined many other immune cytokines involved in the anti-tumor response of CT26, such as IL-12, from Th1 cells; IL-6 from antigen-presenting cells; and TNF-α from macrophages." (PMID 31456687, 2019). "In the absence of T cells or in the presence of only CD4+ or CD8+ T cells, TNFα‐CSG treatment did not significantly reduce tumour weight and volume." (PMID 31709774, 2019). "Macrophage chemoattractant chemokines MCP-1 (CCL2) and RANTES (CCL5): In a rat model of cancer and in human monocytes in vitro, Josephs and colleagues demonstrated, that IgE crosslinking triggered a TNFα/MCP-1 axis, which resulted in recruitment of macrophages into tumours." (PMID 30956175, 2019). "In order to further clarify the role of NF-κB activation in the anti-tumor activity of sorafenib in RCC, Bay 11–7082 (inhibitor of NF-κB, which decreases NF-κB by inhibiting TNF-α-induced phosphorylation of IκB-α) was used for combination with sorafenib in Ketr-3 cells." (PMID 31426831, 2019). "The nanosystem abrogated IL expression, shut down after CCL22 secretion, and restricted Treg cell accumulation within the tumor site to induce sufficient antitumor immune responses (i.e., activated sufficient CD8+ T cells, IFN-γ, and TNF-α) with X- and NIR-induced therapeutic effects." (PMID 31660068, 2019). "G-CSF and GM-CSF are approved as immunoreconstituting agents and TNF-α as an oncotoxic factor rather than to augment the anti-tumor immune responses." (PMID 31179236, 2019). "The antitumor immune response was amplified by photodynamic therapy (PDT), where it effectively eradicated the tumor and distant metastasis in B16-F10 melanoma model by promoting cytokine secretion (TNF-α and IFN-γ) and the frequency of the tumor infiltrating lymphocytes (CD8+ and CD4+)." (PMID 31754376, 2019). "The recruitment of TAN is achieved through the release of specific chemokines from the tumor microenvironment—CXCL1, CXCL2; cytokines—INF- γ, TNF-α; growth factors—granulocyte colony stimulating factor (G-CSF) and presence of specific adhesion molecules on the EC surface." (PMID 30680411, 2019). "An example is NGR-TNF, a chimeric protein that couples the tumor homing peptide CNGRCG, which targets aminopeptidase N or myeloid plasma membrane glycoprotein CD13, also expressed in angiogenic vessels, with the N-terminus of the tumor necrosis factor-α (TNF)." (PMID 31799190, 2019). "Pro-tumor: CLL cells induce ILC1s produce IFNγ and TNFα and form immunosuppressive environment." (PMID 32117199, 2019). "As for TNF-α, it is one of the most important cytokines that can induce tumor necrosis without significant toxicity to normal cells." (PMID 31552194, 2019). "Tumor-induced osteoclastogenesis was resistant to RANKL and TNF-α inhibitors." (PMID 31835378, 2019). "TNF-α and TGF-β are important inflammatory factors in the tumor microenvironment." (PMID 31109341, 2019). "When MDA-MB-231:MSC co-cultures were established without TNFα stimulation, the tumor cells were almost the exclusive source for the chemokine (Figure 3A1)." (PMID 31105691, 2019). "Furthermore, 7 days after the second tumour was introduced, serum cytokines, including IFN-γ and TNF-α, that play vital roles in cellular immunity against cancer, were analysed by ELISA." (PMID 31048681, 2019). "Additionally, CD4 + CD25 + Treg cells secrete TGF-β and IL-10 to suppress effector T cells such as CD8 + cytotoxic T lymphocytes infiltrating the tumor into HCC secreting anti-tumor effector molecules such as IFN -γ, IL-2 and TNFα." (PMID 31600917, 2019). "Moreover, as compared with HCC group, CD56 expression was significantly reduced, while TNF-α and IL-6 expression was increased in the HCC-hMSCs group, which is suspected to contribute to tumor growth and metastasis." (PMID 31142737, 2019).
tumor (continued). "Although our 19305DP-TCR-transduced CD4+ T cells showed moderate cytotoxicity, it is possible that production of anti-tumor effector cytokines such as IFN-γ and TNF-α from CD4+ T cells may damage cancer cells." (PMID 30626427, 2019). "In the present study, when cells were additionally stimulated with TNF-α before IR, the tumour cell adhesion to EC clearly increased compared to nonstimulated cells, but the same dose-dependencies were observed." (PMID 31565662, 2019). "Quite recently, TGF-β and TNFα have been shown to mediate the expression of the zinc transporter ZIP14, that is overexpressed in the skeletal muscle of both cachectic tumor-bearing animals and patients affected by metastatic cancer and that plays a causative role in muscle wasting." (PMID 30833900, 2019). "To understand which molecules were responsible for this activity we performed experiments of THP1 activation with tumor cell supernatants in the presence of neutralizing Abs and BoxA to inhibit IL-1α, TNF-α, IL-18 and HMGB1, respectively, which are released by tumor cells." (PMID 30760333, 2019). "Univariate analysis revealed that preoperative serum IL6 > 8.45 pg/ml, preoperative serum IL8 > 68 pg/ml, preoperative serum TNF − α > 14.9 pg/ml, MVI, and maximum tumor size > 5 cm were significantly correlated with RFS in HCC patients who accepted radical hepatectomy." (PMID 31781194, 2019). "However, in patients with melanoma, a reverse in tumor-induced T cell exhaustion/dysfunction was achieved via dual blockade of TIM-3 and PD-1, which restored T cell secretion of IFNγ and TNFα." (PMID 30917934, 2019). "We demonstrated that TNFα stimulation of TNBC:MSC “Contact” co-cultures has led to enhanced migration and invasion of TNBC cells, to increased angiogenesis and to higher metastatic potential of the tumor cells in vivo." (PMID 31105691, 2019). "TNF-α is a kind of cell factor produced by activated macrophages which can directly kill tumor cells, but has no obvious toxicity to normal cells." (PMID 31480462, 2019). "Our experience adds to the growing animal literature showing that concurrent anti-TNFα and ICI therapy is safe, does not negatively impact tumor control and is associated with a better side effect profile." (PMID 31439050, 2019). "Our data suggest that TNFα‐CSG treatment, despite the resulting ECM loss, does not increase metastasis, potentially because it reduces tumour hypoxia." (PMID 31709774, 2019). "These exhausted CD8+ T cells express co-inhibitory molecules (e.g., PD-1, LAG-3, TIM-3, TIGIT) and lose the ability to produce multiple cytokines such as interferon (IFN)-γ, tumor necrosis factor (TNF)-α, and interleukin (IL)-2, namely they lose anti-tumor activities." (PMID 30696484, 2019). "Furthermore, CD8 T cells produced increased levels of TNFα and IFNγ in T-PNU treated animals supporting a crucial role for CD8 T cells in T-PNU-mediated tumor rejection." (PMID 30665463, 2019). "IFNγ, TNFα, and TGFβ1 are known to induce genotoxic stress, DDR signaling and senescence in both normal and tumor cells and we hypothesized that the JAK2V617F+ P-ECs are refractory to such treatment." (PMID 30967632, 2019). "The level of TNF-α with M1 was ~10-fold higher than in the co-culture with the primary cell line, indicating that TNF-α production was enhanced with M1 in the presence of metastatic tumor cells." (PMID 31636296, 2019). "VCAM-1 expression could be induced by pro-inflammatory cytokines, such as Tumor Necrosis Factor-α (TNF-α), IL-1 or IL-6, major mediators of tumor progression." (PMID 31340603, 2019). "Interestingly, neural signals initiated by opsonins initiate a neoplasia inflammatory response in the brain, that quickly signals to local pro-inflammatory cytokines IL1B and TNF throughout the body." (PMID 30987199, 2019). "TNFα-mediated iNOS upregulation and NO secretion in neutrophils induce the apoptosis of non-activated CD8+ T cells via direct contact between cells in these tumor contexts." (PMID 31474975, 2019).